RET (ret proto-oncogene)
Diseases named in the same sentence as RET in open-access papers (continued):
Sharing a sentence is not in itself a finding about the gene and the disease.
thyroid cancer (continued). "While RET mutations have been associated with thyroid cancer for many years, the discovery of KIF5B-RET fusions in non-small cell lung cancer (NSCLC) has created particular excitement." (PMID 30038711, 2018). "Ponatinib potently inhibits activating variants of RET in models of thyroid cancer, and others have shown that ponatinib inhibits KIF5B-RET fusions in genetically engineered models (but not patient-derived xenograft [PDX] models)." (PMID 30038711, 2018). "Among the individual, cancer-specific genes that were detected in our graph-based analysis, the well-known RET oncogene has been associated with thyroid cancer progression in numerous studies." (PMID 28178311, 2017). "Using our approach, we were able to associate the increase in RET oncogene expression with a large methylation decrease, contributing to an improved understanding of the etiology of thyroid cancer." (PMID 28178311, 2017). "Association between haplotypes of RET tagSNPs and the occurrence of distant metastasis in thyroid cancer." (PMID 29131865, 2017). "Taken together, these findings confirm that RET exon 8 mutation fMTC is indeed a medium-risk thyroid cancer as also suggested by the recently revised ATA guidelines." (PMID 28951487, 2017). "Risk factors for the type of thyroid cancer that occurs most frequently in teens—papillary thyroid carcinoma—, include ionizing radiation, a mutation to the RET proto-oncogene, and family history." (PMID 28235028, 2017). "Activation of this pathway in thyroid carcinomas is through RET/PTC rearrangement, RAS mutations and BRAF mutations." (PMID 27703585, 2016). "Some identified genetic alterations in patients with thyroid carcinomas are changes in tyrosine kinase domain of RET gene in 15 – 33 %, RAS mutations detected in 10% and B-RAF mutations in 40-60% of cases." (PMID 27703585, 2016). "More well-controlled studies are needed to clarify the potential links between iodine intake and molecular alterations such as mutations of the BRAF and RAS genes and BRAF and RET rearrangements in thyroid cancer." (PMID 26146517, 2015). "Thyroid cancers arise from epithelial cell mutations, such as RET/PTC genetic aberration formed by chromosomal rearrangement of RET tyrosine kinase domain to N-terminal of H4 (D10S170) and frequently associated to radiation derived papillary thyroid cancer." (PMID 26664298, 2015). "We also show that lenvatinib directly inhibits the in vitro proliferation of thyroid cancer cell lines carrying mutations that activate RET or in which FGFR1 is overexpressed." (PMID 25295214, 2014). "RET (rearranged during transfection), is a known oncogene in thyroid cancer, with both activating mutations and gene rearrangements observed." (PMID 25505733, 2014). "Several studies have been associating thyroid cancer with exposure to 131I, which can cause several atypical molecular alterations in genes such as RET, NTRK1, RAS, and BRAF." (PMID 25328756, 2014). "Overexpression of fibroblast growth factor receptor and mutations of RET are reported to participate in the development and aggressive phenotypes of thyroid cancers." (PMID 25295214, 2014). "Our study is the largest reported so far, on the association between differentiated thyroid cancer and polymorphisms at the RET locus." (PMID 25330015, 2014). "Deregulated RET activity has been identified as a causative factor in the development, progression and response to therapy of thyroid carcinoma." (PMID 25409876, 2014). "Mutations in the RET proto-oncogene have been implicated in the pathogenesis of several forms of thyroid cancer." (PMID 23455356, 2013). "On the other hand, BRAF mutations or RET/PTC rearrangements are commonly seen in thyroid cancer arising in struma ovarii." (PMID 22682753, 2012).
thyroid cancer (continued). "Multiple endocrine neoplasia (MEN) type 2 is characterized by thyroid cancer, variable penetrance of tumors or hyperplasia in other endocrine organs and mutations in RET, the receptor tyrosine kinase proto-oncogene “rearranged during transfection”." (PMID 22359510, 2012). "This is exemplified by heterozygous gain of function mutations in RET which are associated with thyroid carcinoma and multiple endocrine neoplasia types 2A and 2B versus homozygous loss of function mutations in Hirschsprung disease." (PMID 21931569, 2011). "Inhibitors of BRAF kinase block the growth of thyroid cancer cells that have RET/PTC or BRAF mutations." (PMID 20628483, 2010). "In thyroid cancer cell lines with RET/PTC or BRAF oncogenic mutations cyclinD1-CDK4 complex is more abundant than cyclinD3-CDK4, suggesting the dominant character of cyclin D1 complexes formation in thyroid oncogenesis." (PMID 19878585, 2009). "Selpercatinib (SEL) is a selective RET (rearranged during transfection) inhibitor that has a good safety profile and potent antitumor effects against RET mutation-positive medullary thyroid carcinoma and RET fusion gene-positive thyroid carcinoma, as demonstrated by the LIBRETTO-001 trial." (PMID 41869262, 2026). "However, in human PTC, an association between tumor subtype and genetic lesion is only rarely encountered, e.g., RET/PTC3 rearrangement is more frequent in the solid variant of PTC being overrepresented in radiation-induced thyroid cancer." (PMID 39956582, 2025). "We therefore investigated whether KEAP1 loss modulates the sensitivity of thyroid cancer cells to targeted RET inhibition." (PMID 41573641, 2025). "The combination of selpercatinib and crizotinib has achieved successful outcomes in overcoming drug resistance in the treatment of non-small cell lung cancer, providing an important reference for combination therapy in thyroid cancer patients with RET mutations." (PMID 41278287, 2025). "For instance, genetic markers like BRAF mutations or RET/PTC rearrangements are known to play a critical role in thyroid cancer, and their inclusion could improve the framework’s ability to identify malignancies." (PMID 40989437, 2025). "In addition, other classical fusions associated with differentiated thyroid cancer, such as rearrangement involving the RET gene (RET/PTC), appear to activate the PI3K/AKT pathway." (PMID 39199391, 2024). "In addition, RET mutations are drivers in 60% of sporadic medullary thyroid cancers and 99% of hereditary thyroid cancers." (PMID 37360768, 2023). "In humans, RET is suggested to be associated with diverse subtypes of thyroid cancers." (PMID 37742294, 2023). "Thus, the major challenges ahead in the effective treatment of RET-driven thyroid cancer are to identify patients at high risk of poor outcomes, their specific RET alterations, and to provide appropriate treatment and follow up." (PMID 37207147, 2023). "PTC accounts for 85% of thyroid cancer and is the first human cancer associated with RET fusion." (PMID 36865807, 2023). "Interestingly, although RET mutation is rarely observed in follicular cell-derived thyroid cancers, RET fusion occurs frequently in PTC and PDTC, particular in the patients with young age and environmental radiation exposure." (PMID 37081420, 2023). "Thyroid cancer is associated with a broad range of different mutations, including RET fusion genes." (PMID 37882481, 2023). "Additionally, updated guidelines for the genomic profiling of patients with advanced and progressive thyroid cancer will facilitate molecular-targeted treatment according to driver gene alterations, such as RET mutation or fusion." (PMID 37207147, 2023). "A more cost-effective approach using mutational exclusivity of RET fusions with other driver mutations could be applied in adult thyroid carcinomas." (PMID 37882481, 2023).
thyroid cancer (continued). "The RET pathogenic variant (ENST00000355710.3) c.1900T>C) was identified in three related cases with a family history of thyroid cancer, providing a diagnosis of multiple endocrine neoplasia type 2 (MEN2), which is characterized by the development of medullary thyroid carcinoma." (PMID 36428697, 2022). "In 1985, the RET gene was discovered as the most frequent mutated gene in thyroid cancer." (PMID 35631627, 2022). "In summary, our results demonstrate a high frequency of NTRK fusions and RET fusions/mutations in patients with thyroid cancer with RAI-resistant distant metastases, ATA high, or ATA intermediate risk of recurrence, whose tumors are negative for other mutations/fusions." (PMID 34981751, 2022). "We assumed the reason may be that other gene aberrations exist, such as RAS mutation and RET rearrangements of thyroid cancer, which have been reported to activate the MAPK pathway, followed by the dedifferentiation of DTCs." (PMID 36407316, 2022). "Eight participants with a RET variant from three families had a self-reported family history consistent with the variant, including a family history of a medullary thyroid cancer, unknown thyroid cancer, and/or clinically identified RET variant." (PMID 35668420, 2022). "This approach may be especially effective in patients harboring mutations/activation of both the RET gene and the hTERT promoter, such as thyroid cancer patients." (PMID 36142729, 2022). "In a coculture model with monocytes from patients harboring PTEN mutation and thyroid cancer cells TPC1 (RET/PTC rearrangement) or FTC-133 (PTEN deficient), metformin did not alter secretion of proinflammatory cytokines from TAM induced by thyroid cancer cells." (PMID 35327549, 2022). "Selpercatinib was approved for use in the U.S. in May 2020 for patients with RET-fusion positive non-small cell lung cancer, RET-fusion positive thyroid cancer, or RET-mutation positive meduallary thyroid cancer." (PMID 33402119, 2021). "According to recent reports, such mutation pattern may also distinguish certain tumor types from the other ones, which has been validated to be pathogenic in a specific oncogene named RET for thyroid carcinoma, confirming our prediction." (PMID 34513841, 2021). "Genetic alterations that are already known occurred in thyroid cancer such as, RET/PTC (20%), all-RAS mutation (10%), and TRK (<5%) that might be present in our specimens but were not evaluated by this study." (PMID 33247684, 2020). "However, in the recent pan-cancer analysis of whole genomes, it was found that 4 of the 13 fusion genes identified in thyroid carcinoma, including 2 RET fusions, were caused by chromoplexy." (PMID 32326537, 2020). "Unlike the case of familial medullary thyroid cancer, in which there is extensive evidence linking germline point mutations in the RET proto-oncogene to the development of thyroid cancer, the genetic causes for FNMTC remain largely unknown." (PMID 31614935, 2019). "N-desmethylvandetanib and vandetanib-N-oxide were identified as the two major oxidation products of vandetanib, the drug used for the treatment of symptomatic or progressive medullary thyroid cancer due to the RET tyrosine kinase mutation occurring in this type of thyroid cancer." (PMID 31295928, 2019). "Specifically, two tyrosine kinase inhibitors (TKI), the VEGFR2/EGFR inhibitor vandetanib and VEGFR2/MET inhibitor cabozantinib, are approved for treatment of advanced thyroid cancer, and have been evaluated in clinical trials for RET-associated lung adenocarcinoma." (PMID 30666215, 2018). "Association between haplotypes of RET tagSNPs and susceptibility to thyroid cancer." (PMID 29131865, 2017). "Association between RET tagSNP and clinicopathological features of thyroid cancer." (PMID 29131865, 2017).
thyroid cancer (continued). "And our study population is relatively small, especially for the haplotype analysis for distant metastasis in thyroid cancer; thereby, impact of RET SNPs on disease risk and disease severity might be probably underestimated." (PMID 29131865, 2017). "Association between RET tagSNP and susceptibility to thyroid cancer." (PMID 29131865, 2017). "At a concentration of 10 nM, ALW-II-41-27, XMD15-44 and HG-6-63-01 inhibited RET kinase and signaling in human thyroid cancer cell lines carrying oncogenic RET alleles; they also inhibited proliferation of cancer, but not non-tumoral Nthy-ori-3-1, thyroid cells, with an IC50 in the nM range." (PMID 26046350, 2015). "EGFR mutations contribute to RET activation in thyroid cancer." (PMID 25789503, 2015). "Further studies with larger populations, including cases of FTC, may prove useful to assess the role of RET polymorphisms in differentiated thyroid cancer." (PMID 25330015, 2014). "A variant located on 14q13.3 nearest to thyroid transcription factor-1 (TTF1) predisposes individuals to thyroid cancer, but whether this variant is related to the RET/PTC rearrangement associated with human papillary thyroid carcinomas (PTCs) is unknown." (PMID 24014739, 2013). "Furthermore, in WRO cells, another thyroid cancer cell line with RET/PTC mutation, cells stably transfected with XB130 shRNA reduced tumor growth in nude mice." (PMID 22928011, 2012). "Therefore, supposed markers of the radiation-induced thyroid cancer, such as the RET rearrangements, are probably associated with disease duration and tumor progression." (PMID 22175034, 2012). "A common mutation found in thyroid cancer is RET/PTC chromosomal rearrangements." (PMID 22928011, 2012). "In addition, RET/PTC is more prevalent in childhood thyroid cancers, whereas BRAF V600E mutations are extremely rare in children and the age of patients with PTCs who express BRAF V600E is more than that of the general PTC population." (PMID 17179987, 2007). "Therefore the activation of RET seems to be a somatic cell mutation specific to human thyroid carcinomas." (PMID 8353035, 1993). "The RET inhibitor selpercatinib has recently been approved for lung and thyroid cancers harbouring RET gene mutations or fusions, and pralsetinib has been recently reported to be a new, well-tolerated, promising treatment option for patients with RET fusion-positive LACs." (PMID 34282766, 2021). "In the case of RET as an oncogene the results presented herein might be of clinical benefit as cytosolic Ca2+ signaling is implicated in general cancer growth as well as in thyroid cancers of the MEN2b type." (PMID 22355350, 2012). "Selpercatinib (Retevmo) is a selective rearranged during transfection (RET) kinase inhibitor approved for RET-altered malignancies, including thyroid carcinoma." (PMID 42005101, 2026). "We show that loss of KEAP1 reduces sensitivity of RET fusion-positive PTC cells to the receptor tyrosine kinase inhibitor selpercatinib, a key therapeutic agent for RET-driven thyroid cancers." (PMID 41573641, 2025). "Although both drugs have the ability to inhibit RET—a common driver gene in thyroid cancer —lenvatinib is considered more potent." (PMID 40605011, 2025). "Overall, the clonal nature and mutual exclusivity of genetic alterations in BRAF, RAS, RET, and other key genes indicate that a single genetic change is the primary initiating event in most thyroid cancers, with impressive genotype–phenotype correlation." (PMID 41175860, 2025). "RET (REarranged during Transfection) alterations are considered oncogenic drivers in different type of cancers such as lung and thyroid cancer." (PMID 41465387, 2025). "In the future, the field should focus on several key areas: developing next-generation inhibitors against drug-resistant mutations; optimizing combination regimens, including with immunotherapy; and expanding research into RET-altered thyroid cancer subtypes." (PMID 41278287, 2025).
thyroid cancer (continued). "RET mutations have long been associated with multiple endocrine neoplasia type 2 (MEN2) and thyroid cancers." (PMID 41373672, 2025). "The development of RET inhibitors has shown impressive outcomes and is now established as a standard-of-care treatment option for lung and thyroid cancer." (PMID 40332427, 2025). "The focus will be on clinical trials of RET inhibitors in thyroid cancer, drawing on the extensive insights gained from their use in NSCLC." (PMID 39655713, 2025). "Consistent with the previous report, the prevalence of RET fusion in thyroid cancer is 3.11% (7/225), while the occurrence of NTRK3 fusion in thyroid cancer is infrequent, with a frequency of 0.95% (2/225) in our study." (PMID 40586006, 2025). "In thyroid cancer, the clinical relevance of RET fusions extends beyond targeted therapy with RET TKIs." (PMID 41465145, 2025). "The mean TMB was 4.0 ± 1.9 for RET+ NSCLC (N = 65), 2.6 ± 1.6 for RET+ thyroid cancer (N = 52), both of which were significantly lower than RET+ CRC." (PMID 39950716, 2025). "Similar to other malignancies, the emergence and advancement of thyroid cancer are accompanied by genetic mutations, such as RAS, BRAF, or TERT mutations, as well as RET and NTRK rearrangements." (PMID 40586006, 2025). "For previously treated RET fusion-positive NSCLC, RET-mutant medullary thyroid cancer, and RET fusion-positive thyroid cancer, the ORR was 64%, 69% (1-year PFS of 82%), and 79% (1-year PFS of 64%)." (PMID 41374970, 2025). "Despite only five cases, the incidence of RET mutations in MTC remains at 20%, which is higher than in other types of thyroid cancer." (PMID 40805132, 2025). "Another RET inhibitor, pralsetinib, which has shown efficacy in lung cancer, has also been studied in patients with thyroid cancer with this genetic alteration." (PMID 39744583, 2025). "The selected threshold parameters for RET coverage imbalance in RNA-seq were subsequently validated in an independent cohort of 79 thyroid cancer samples." (PMID 41373459, 2025). "Estrogen activates both genomic and non-genomic pathways linked to MAPK and PI3K signaling—the same pathways frequently mutated in thyroid cancer through BRAF, RAS, and RET alterations." (PMID 41595456, 2025). "The most commonly used selective RET inhibitor for the treatment of thyroid cancer is selpercatinib (n = 8, including drug combinations hereafter), followed by pralsetinib (n = 3)." (PMID 41278287, 2025). "An investigation was conducted to identify RET coverage disparities in a substantial collection of experimental RNA-seq data (n = 1327 profiles, comprising 154 non-small cell lung cancer and 221 thyroid cancer samples)." (PMID 41373459, 2025). "Some small-molecule targeted agents, such as sorafenib and vandetanib, have been shown to be therapeutic for RET-PTC-positive thyroid cancer patients." (PMID 40584293, 2025). "The emergence of selective RET inhibitors has led to revolutionary breakthroughs in the treatment of thyroid cancer." (PMID 41278287, 2025). "It was further assessed in the prospective analysis of patients with diverse RET fusion-positive tumors, excluding RET fusion-positive NSCLC or thyroid cancer." (PMID 41374970, 2025). "Deleteriousness scores calculated using CADD revealed several variants with very high scores, including those in RGPD3, LRP1B, and RET, emphasizing their critical roles in thyroid cancer progression and therapeutic potential." (PMID 40297138, 2025). "The identification of driver mutations that activate this pathway, such as BRAF, RAS mutations and RET/PTC rearrangements, has provided critical insights into thyroid cancer biology and facilitated the development of targeted therapies." (PMID 39874138, 2025). "Surgical resection is usually the treatment of choice for most patients with RET-PTC-positive thyroid cancer." (PMID 40584293, 2025). "Selpercatinib is a selective RET tyrosine kinase inhibitor approved for use in RET fusion-positive thyroid cancers." (PMID 41573641, 2025).